CCNH (cyclin H)
Description:
Component of the CDK-activating kinase (CAK) complex, a master regulator of CDK activity by catalyzing the activating threonine phosphorylation of CDKs. Binds and activates cyclin-dependent protein kinase CDK7, the catalytic subunit of CAK. CAK activates major mediators of cell cycle control, including CDK1, CDK2, CDK4 and CDK6, and plays a key role in regulating cell cycle progression. CAK complexed to the core-TFIIH basal transcription factor activates RNA polymerase II by serine phosphorylation of the repetitive C-terminal domain (CTD) of its large subunit (POLR2A), allowing its escape from the promoter and elongation of the transcripts. Involved in cell cycle control and in RNA transcription by RNA polymerase II. Its expression and activity are constant throughout the cell cycle.
Synonyms: p34; p37; CycH; CAK
Tractability: Small molecule: a structure with a bound ligand is known; a high-quality ligand is known; it belongs to a druggable protein family. PROTAC: ubiquitination databases record sites on it; its protein half-life has been measured.
Target class: Other cytosolic protein
Gene: Protein-coding gene on chromosome 5 (87,318,416 to 87,413,029, reverse strand). Ensembl gene ENSG00000134480.
Subcellular location: Nucleus
Subcellular location (Human Protein Atlas): Nucleoplasm
Pathways (Reactome):
Gene expression (Transcription): Formation of RNA Pol II elongation complex; Formation of the Early Elongation Complex; NoRC negatively regulates rRNA expression; RNA Pol II CTD phosphorylation and interaction with CE; RNA Polymerase I Promoter Escape; RNA Polymerase I Transcription Initiation; RNA Polymerase I Transcription Termination; RNA Polymerase II Pre-transcription Events; RNA Polymerase II Promoter Escape; RNA Polymerase II Transcription Elongation; RNA Polymerase II Transcription Initiation; RNA Polymerase II Transcription Initiation And Promoter Clearance; RNA Polymerase II Transcription Pre-Initiation And Promoter Opening; RUNX1 regulates transcription of genes involved in differentiation of HSCs
Disease: Formation of HIV elongation complex in the absence of HIV Tat; Formation of HIV-1 elongation complex containing HIV-1 Tat; Formation of the HIV-1 Early Elongation Complex; HIV Transcription Initiation; RNA Pol II CTD phosphorylation and interaction with CE during HIV infection; RNA Polymerase II HIV Promoter Escape; Tat-mediated elongation of the HIV-1 transcript; Transcription of the HIV genome
DNA Repair: Dual incision in TC-NER; Formation of Incision Complex in GG-NER; Formation of TC-NER Pre-Incision Complex; Gap-filling DNA repair synthesis and ligation in TC-NER; Transcription-Coupled Nucleotide Excision Repair (TC-NER)
Cell Cycle: Cyclin A/B1/B2 associated events during G2/M transition; Cyclin A:Cdk2-associated events at S phase entry; Cyclin D associated events in G1; Cyclin E associated events during G1/S transition
Metabolism of RNA: mRNA Capping
Gene Ontology:
Molecular function: protein binding; RNA polymerase II general transcription initiation factor activity; cyclin-dependent protein serine/threonine kinase regulator activity; kinase activity
Biological process: protein stabilization; regulation of G1/S transition of mitotic cell cycle; regulation of transcription by RNA polymerase II; transcription initiation at RNA polymerase II promoter; nucleotide-excision repair; DNA-templated transcription
Cellular component: CAK-ERCC2 complex; cyclin-dependent protein kinase holoenzyme complex; nucleoplasm; transcription factor TFIIH core complex; transcription factor TFIIH holo complex; transcription factor TFIIK complex; nucleus
Genetic constraint (gnomAD): Loss-of-function variants: 17 observed, 24.28 expected, observed/expected ratio (o/e) 0.7, 90% interval 0.48 to 1.05. The upper end of that interval is the gene's LOEUF score, 1.05, which puts it in group 4 of 6, group 1 being the genes least tolerant of losing a copy. Missense variants: 272 observed, 296.65 expected, observed/expected ratio (o/e) 0.92, 90% interval 0.83 to 1.01. Synonymous variants: 100 observed, 108.36 expected, observed/expected ratio (o/e) 0.92, 90% interval 0.78 to 1.09.
Homologues: Orthologues: dog CCNH (97% identical), macaque CCNH (97% identical), pig CCNH (97% identical), chimpanzee CCNH (97% identical), guinea pig CCNH (96% identical), rabbit CCNH (96% identical), mouse Ccnh (95% identical), rat Ccnh (93% identical), tropical clawed frog ccnh (66% identical), zebrafish ccnh (65% identical), Drosophila melanogaster CycH (44% identical), Caenorhabditis elegans cyh-1 (31% identical), and 3 more. Paralogues in human: CCNT2 (25% identical), CCNT1 (21% identical), CCNK (20% identical), CCNL2 (18% identical), CCNL1 (17% identical), CCNQ (13% identical).
Diseases named in the same sentence as CCNH in open-access papers:
CCNH is named in the same sentence as 36 diseases in open-access papers, as found by Europe PMC text mining. Sharing a sentence is not in itself a finding about the gene and the disease. The quoted sentences say what the papers report.
breast carcinoma (11 papers, 2010 to 2025). "For instance, CCNH is demonstrated to have an association with cell cycle, apoptosis, DNA repair, cell proliferation, and other signaling pathways in breast cancer." (PMID 33777168, 2021). "Hetal Patel and colleagues also described that Cyclin H expression was associated with a better patient outcome in breast cancer." (PMID 32694938, 2020). "Aberrant expression of cyclin H is shown in multiple tumors, including breast cancer, esophageal cancer, endometrial cancer, and gastrointestinal stromal tumors." (PMID 33777168, 2021). "Abnormal expression of cyclin H is reported in a variety of tumors such as breast cancer, esophageal cancer, endometrial cancer, and gastrointestinal stromal tumors." (PMID 32694938, 2020). "For CCNH-C5orf30, the matching rate of primary breast cancer with lymph node metastases was 62%, while the matching rates for ovarian cancer and colon cancer with their corresponding lymph node metastases were 72% and 73%, respectively." (PMID 30705370, 2019). "Of the 8 regulons identified to be differentially expressed between ER+ and ER- FFPE breast cancer cases, the combination of 4 regulons CCNH+KDM4B-SUV39H2-YEATS2 maximally delineated outcomes in the TCGA breast cancer dataset." (PMID 31856832, 2019). "Breast cancer has extremely high expression of CDK-activating kinase (CAK), a triple complex made up of CDK7, MAT1, and Cyclin H develops." (PMID 40361480, 2025). "The expression of CDK7 and its cofactors cyclin H and MAT1 was found to be elevated in breast cancer compared with normal breast tissue." (PMID 33686962, 2021). "Among them, the CCNH-C5orf30 and TRMT11-GRIK2 gene fusions were found in breast cancer, colon cancer, non-small cell lung cancer, esophageal adenocarcinoma, glioblastoma multiforme, ovarian cancer and liver cancer, with frequencies ranging from 12.9% to 85%." (PMID 30705370, 2019). "CDK14 has been shown to interact with other cyclins as well, such as cyclin B to activate the Wnt pathway in breast cancer, cyclin D3 to regulate cell cycle progression and proliferation in mammalian cells, and the CDK7/cyclin H complex to regulate proliferation and migration in esophageal cancer." (PMID 34571979, 2021). "CDK7, Cyclin H, and MAT1 protein and mRNA expression were found to be upregulated in breast cancer tumors, compared to matched adjacent normal breast tissue, particularly in ER+ breast cancer." (PMID 32155786, 2020).
liver cancer (4 papers, 2019 to 2025). An epithelial or non-epithelial malignant neoplasm that arises from the liver. "Among the eight fusion genes, MAN2A1-FER, TRMT11-GRIK2, and CCNH-C5orf30 were shown as the most frequent in HCC samples, and the relative fusion transcripts in the serum samples of liver cancer patients were identified as circulating, cell-free RNA." (PMID 39941182, 2025). "In this study, we showed that the fusion transcripts of MAN2A1-FER, CCNH-C5orf30 and SLC45A2-AMACR were detected in the serum samples of liver cancer patients as circulating cell-free RNA." (PMID 31164957, 2019).
lung carcinoma (4 papers, 2014 to 2021). "We conducted Kaplan-Meier method analysis (log-rank test) on TCGA database to explore the association between CCNH expression and prognosis in lung cancer." (PMID 33777168, 2021). "Also, we found that overexpression of CCNH was associated with worse first progression in lung cancer samples." (PMID 33777168, 2021). "CCNH was related to poor prognosis, suggesting that CCNH regulated the tumorigenesis and development of lung cancer." (PMID 33777168, 2021). "To sum up, we validated CCNH expression and function in lung cancer progression through bioinformatics analysis and functional assays for the first time." (PMID 33777168, 2021). "The effect of CCNH expression on lung cancer progression was studied by in vitro functional experiments." (PMID 33777168, 2021). "Perhaps, CCNH becomes one of the most valuable prognostic and therapeutic biomarkers of lung cancer." (PMID 33777168, 2021). "Nevertheless, the clinical significance and biological function of cyclin H in lung cancer are yet elusive." (PMID 33777168, 2021). "Quantitative reverse transcription-polymerase chain reaction (qRT-PCR) was used to detect the expression levels of CCNH in 6 lung cancer tissues and 3 cancer cell lines." (PMID 33777168, 2021). "Database analysis screened out candidate oncogenes, and CCNH was of great significance to the tumorigenesis of lung cancer." (PMID 33777168, 2021). "The qRT-PCR data illustrated that the CCNH expression level was largely increased in lung cancer tissues and cells." (PMID 33777168, 2021). "CCNH-C5orf30 was more frequent in lung cancer adenocarcinomas versus squamous type (67.7% versus 34.8%, p = 0.001) and colon cancer at advanced stages at the time of diagnosis (52.3% versus 18.8%, p = 0.037)." (PMID 30705370, 2019). "We discussed the expression of CCNH in lung cancer and its relationship with clinical parameters." (PMID 33777168, 2021). "Here, our study tried to study the mode of action of CCNH in lung cancer patients." (PMID 33777168, 2021). "The higher the expression of CCNH was, the lower the survival rate of lung cancer patients were." (PMID 33777168, 2021). "In this study, we also detected the level of CCNH in lung cancer tissues." (PMID 33777168, 2021). "Our study suggested that CCNH was a promising biomarker and target in the treatment of lung cancer." (PMID 33777168, 2021). "CCNH was an important indicator of poor prognosis for lung cancer patients." (PMID 33777168, 2021). "Our study displayed that CCNH might display as an oncogene in lung cancer and induce its tumor viability, invasion, and migration." (PMID 33777168, 2021). "We analyzed the correlation between CCNH and the clinical characteristics of lung cancer patients." (PMID 33777168, 2021). "Our data revealed that CCNH highly expressed in lung cancer cell lines and tissues." (PMID 33777168, 2021). "CCNH might play an oncogenic role in lung cancer progression." (PMID 33777168, 2021). "Reduced CCNH could inhibit lung cancer cell growth, migration, and invasion." (PMID 33777168, 2021). "Besides, we will conduct in vivo experiments to further explore the role of CCNH in lung cancer." (PMID 33777168, 2021). "However, the exact role of CCNH in the tumorigenesis of lung cancer remains unclear." (PMID 33777168, 2021). "Thus, we predicted that CCNH might be a promising target therapy for lung cancer." (PMID 33777168, 2021). "In this study, transcriptome profiling and RT-qPCR validation revealed that PGL arrests the cell cycle via downregulation of the expression of RB1, CCNH, MDM2, ACCN4, CCND2, GADD45A, and GADD45B in lung cancer cells." (PMID 27355352, 2016).
prostate carcinoma (4 papers, 2015 to 2023). A carcinoma that arises from epithelial cells of the prostate gland. "Only small percentages of blood samples from the prostate cancer patients were positive for CCNH-C5orf30 (5.4% or 8/147), mTOR-TP53BP1 (4.1% or 6/147) and KDM4B-AC011523.2 (1.4% or 2/147)." (PMID 34417538, 2021). "Nine prostate cancer samples were positive for CCNH-c5orf30." (PMID 34417538, 2021). "CDK7 is positively regulated through complex formation with Cyclin H and MAT1, and also, these two were significantly overexpressed in prostate cancer tissue when compared to normal samples." (PMID 36401094, 2023). "CCNH-c5orf30 and mTOR-TP53BP1 had low detection rates, positive in only 5.4% and 4% of the blood samples from the prostate cancer patients." (PMID 34417538, 2021).
colon cancer (3 papers, 2019 to 2022). "SNPs in CCNH, encoding cyclin H, involved in cell cycle progression and DNA repair, were associated with CIPN in 206 colon cancer patients, and in 228 gastrointestinal cancer patients treated with oxaliplatin." (PMID 35360655, 2022).
gastrointestinal stromal tumor (3 papers, 2020 to 2024). "Consistent with our research, cyclin H positivity was significantly associated with the reduced disease-specific survival in patients with gastrointestinal stromal tumors." (PMID 32694938, 2020).
ovarian carcinoma (3 papers, 2019 to 2022). A malignant neoplasm originating from the surface ovarian epithelium. "In this study, we demonstrate the high expression of cyclin H in ovarian cancer and the association of cyclin H with the unfavorable clinicopathologic variables of patients." (PMID 32694938, 2020). "Cyclin H was slightly expressed in grade 1 ovarian cancer but highly expressed in grade 2 and grade 3 cancerous tissues." (PMID 32694938, 2020). "Tumor’s weight and size in the cyclin H shRNA group was much lighter and smaller, respectively than those in the control group, indicating that cyclin H knockdown significantly reduced ovarian cancer growth." (PMID 32694938, 2020). "The function of cyclin H in ovarian cancer was further explored using HO8910 cells and a subcutaneous xenograft model of nude mice." (PMID 32694938, 2020). "Immunohistochemical staining was used in this study to evaluate the expression of cyclin H in 60 pathological specimens of ovarian cancer with different grades." (PMID 32694938, 2020). "Cyclin H was slightly expressed in grade 1 ovarian cancer while highly expressed in high grade 2 and grade 3 samples." (PMID 32694938, 2020). "Here, we observed that cyclin H was positively correlated with the increased tumor grade of ovarian cancer and the expression of the proliferation markers Ki-67 and p-CDK2." (PMID 32694938, 2020). "Silencing cyclin H resulted in a G1/S cell cycle arrest in ovarian cancer cells suppressing its growth." (PMID 32694938, 2020). "Immunohistochemical staining was performed on 60 ovarian cancer cases, and a correlation between cyclin H expression and the clinical characteristics of ovarian cancer was analyzed." (PMID 32694938, 2020). "This investigation aims to characterize the clinical significance and the biological functions of cyclin H in ovarian cancer." (PMID 32694938, 2020). "Animal experiments confirmed that cyclin H has a positive regulatory role in ovarian cancer, and the knockdown of cyclin H suppresses the growth of tumors in nude mice." (PMID 32694938, 2020). "Considering the reports of the controversial role of cyclin H in different kinds of tumors, more in-depth, systematic studies are needed to confirm the therapeutic value of cyclin H in ovarian cancer." (PMID 32694938, 2020). "This study revealed that cyclin H is highly expressed in high-grade ovarian cancers and promotes the growth of ovarian cancer by regulating the cell cycle." (PMID 32694938, 2020). "We confirmed the role of cyclin H in ovarian cancer in vivo using a subcutaneous nude mouse tumor model." (PMID 32694938, 2020). "Additionally, we down-regulated the expression of cyclin H in ovarian cancer cells using shRNA and explored its effect on cell cycle and tumor growth." (PMID 32694938, 2020). "In the ovarian cancer tissues, cyclin H is localized in the nucleus and the cytoplasm." (PMID 32694938, 2020). "The Ki67 expression was also decreased in cyclin H silenced ovarian cancer." (PMID 32694938, 2020). "However, with our protein and mRNA data, we arrived at an opposite conclusion in the case of ovarian cancer, where the five-year survival rate in cyclin H low patients was significantly higher than in the cyclin H high patients." (PMID 32694938, 2020). "This study reveals a candidate that helps in early diagnosis or predicts prognosis of ovarian cancer and also provides evidence to support the therapeutic value of cyclin H in ovarian cancer, which may help in improving the diagnosis and the prognostic classification of ovarian cancers." (PMID 32694938, 2020). "However, the clinical significance and the biological function of cyclin H in ovarian cancer remains unclear." (PMID 32694938, 2020). "In addition, CCNH was related to the promotion of cancer cell migration, and RPA2 expression was an independent predictor of adverse outcome in ovarian cancer." (PMID 35769257, 2022).
ovarian carcinoma (continued). "Similarly, the expression of cyclin H, MAT1, CDK7, and p-CDK2 also decreased in cyclin H silenced ovarian cancer." (PMID 32694938, 2020). "The Spearman’s rank correlation analysis showed that the expression of cyclin H is positively correlated with the tumor grade, the FIGO stage, histological grade, and the peritoneal metastasis of ovarian cancer and is also positively correlated with the Ki67 and p-CDK2 in ovarian cancer." (PMID 32694938, 2020). "Additionally, we found that the five-year survival rate was higher in patients expressing low cyclin H than those expressing high cyclin H. Further, knockdown of cyclin H was achieved using an shRNA in HO8910 ovarian cancer cell line." (PMID 32694938, 2020). "To determine whether the expression of cyclin H predicts the survival of ovarian cancer patients or not, we analyzed the relationship of cyclin H protein and the mRNA expression with the survival of ovarian cancer patients." (PMID 32694938, 2020).
esophageal squamous cell carcinoma (2 papers, 2021 to 2024). Esophageal squamous cell carcinoma (ESCC) is a type of esophageal carcinoma (EC) that can affect any part of the esophagus, but is usually located in the upper or middle third. "CCNH is greatly associated with poor clinical-pathological variables in human esophageal squamous cell carcinoma (ESCC) and functions importantly in ESCC tumorigenesis and development." (PMID 33777168, 2021).
HCMV infection (2 papers, 2016 to 2022).
anemia (1 paper, 2017). A reduction in the number of red blood cells, the amount of hemoglobin, and/or the volume of packed red blood cells. "We also found rs2290280 in CCNH was significantly associated with anemia in SCC subgroup." (PMID 28924235, 2017).
fungal infection (1 paper, 2024). "Collectively, our study reveals that a secreted fungal toxin acts to hijack the canonical DNA damage repair pathway by targeting CCNH and to promote fungal infection." (PMID 38413612, 2024). "Therefore, more functional insights into the mechanism of candidalysin-induced CCNH mediated fungal infection might elucidate its role in tumor progression." (PMID 38413612, 2024).
glioma (1 paper, 2017). A benign or malignant brain and spinal cord tumor that arises from glial cells (astrocytes, oligodendrocytes, ependymal cells). "Up-regulated genes included the glioma related genes SEC61G and LNX1 and the cell cycle related SERTAD1 and CCNH." (PMID 29163818, 2017).